IL10 (interleukin 10)
Diseases named in the same sentence as IL10 in open-access papers (continued):
Sharing a sentence is not in itself a finding about the gene and the disease.
paracoccidioidomycosis (8 papers, 2011 to 2024). A systemic fungal infection caused by Paracoccidioides brasiliensis that is most often seen in immunocompromised patients. "On the other hand, IL-10 is a potent anti-inflammatory cytokine that is generally associated with increased infection in paracoccidioidomycosis." (PMID 31340551, 2019). "This led us to investigate the innate and adaptive aspects of immunity in pulmonary paracoccidioidomycosis using IL-10-deficient mice in comparison with their IL-10-normal counterparts." (PMID 24205424, 2013). "Considering these, we have evaluated the influence of TLR4 on the expression of IL-10 by MDSCs in murine paracoccidioidomycosis." (PMID 39035356, 2024). "These evidences on the detrimental effects of IL-10 to pulmonary paracoccidioidomycosis suggest that therapeutic measures aimed to control IL-10 production or activity could exert a protective effect to this severe fungal pathology." (PMID 24205424, 2013). "Since suppressive effects of IL-10 during paracoccidioidomycosis is well established, we propose that the presence of IL-10 during the first 15 days is essential to establish a initial negative regulation of immune cells via down-regulation of APC function or via Treg induction." (PMID 21731741, 2011). "Furthermore, the mild or regressive forms of paracoccidioidomycosis have been associated with decreased or absence of IL-10 production, respectively." (PMID 26635449, 2015). "Mild or moderate chronic forms of paracoccidioidomycosis are now believed to occur in the context of Th17/Th22 lymphocytes and a mixture of cytokines IL-17 and IL-22 (high levels), IFN-γ, TNF-α, IL-2 and IL-10 and IL-4 (variable levels) and with high levels of IgG1 antibodies." (PMID 33668671, 2021).
periapical granuloma (8 papers, 2015 to 2025). Chronic nonsuppurative inflammation of periapical tissue resulting from irritation following pulp disease or endodontic treatment. "Subsequently, immunohistochemical (IHC) staining unraveled elevated IL-1β expression in radical cysts (RCs) relative to periapical granulomas (PGs), whereas the expression levels of Mertk, Gas6, and IL-10 were more pronounced in PGs than in RCs." (PMID 41155449, 2025). "Specifically, IL-1β expression was higher in radical cysts (RCs) than in periapical granulomas (PGs), while the expression of IL-10 was stronger in PGs than in RCs." (PMID 38612664, 2024). "IL-10 was significantly high in periapical granuloma, radicular cyst (P < 0.01), and periapical abscess (P < 0.05) in comparison with healthy controls." (PMID 34539639, 2021). "On estimation of IL-21 levels in periapical granulomas, it was demonstrated that IL-21 along with IL-17A, TNF-α (tumour necrosis factor-α), and IFN-γ were higher in active periapical granulomas, while IL-4, IL-9, IL-10, and IL-22 were higher in inactive periapical granulomas." (PMID 26998377, 2016). "The functional role of EBER in periapical granulomas is unclear; however, it has been demonstrated that EBER induces transcription of cytokines, including IL-10, insulin-like growth factor-1, and IL-9." (PMID 25884725, 2015).
peripheral nerve injury (8 papers, 2019 to 2025). Injury to a peripheral nerve. "Altogether these results indicate that the antinociceptive effect of exogenous and endogenous IL-27 upon neuropathic pain caused by peripheral nerve injury depends on the induction of IL-10 expression on myeloid cells in the DRGs." (PMID 32047492, 2019). "Anti-inflammatory interleukins, such as IL-4, IL-10, and IL-13, play a critical role in enhancing the repair microenvironment following peripheral nerve injury." (PMID 41573554, 2025). "After nerve injury, IL-13 induces macrophages to produce IL-10, which in turn reduces the excitability and spontaneous activity of peripheral sensory neurons, facilitating the resolution of peripheral nerve injury." (PMID 41573554, 2025). "A robust peripheral immune response and the anti-inflammatory cytokine interleukin-10 (IL-10) are critical for maximal facial motoneuron (FMN) survival after peripheral nerve injury." (PMID 36231129, 2022). "Other studies have also reported a role of IL-10 for pain resolution and functional recovery after peripheral nerve injury, indicating the general importance of anti-inflammatory responses for pain resolution." (PMID 33692810, 2021). "After peripheral nerve injury, IL-10 plays a role in controlling the early influx and the later efflux of macrophages out of the nerve via downregulating expression of proinflammatory chemokines and cytokines." (PMID 31194740, 2019). "Through the sustained and direct release of IL-10, it promotes the transformation of pro-inflammatory macrophages into an anti-inflammatory phenotype, thereby accelerating the resolution of inflammation and facilitating the recovery process after peripheral nerve injury." (PMID 41573554, 2025). "The cytokines IL6, TNF, IL10, IL2, and IL4 are all immunomodulatory factors, among which TNF and IL-6 have been confirmed to be involved in the pathological process of peripheral nerve injury." (PMID 33299447, 2020).
post-traumatic stress disorder (8 papers, 2019 to 2023). An anxiety disorder precipitated by an experience of intense fear or horror while exposed to a traumatic (especially life-threatening) event. "These tau elevations were associated with chronic post-concussive symptoms, while higher IL-10 levels were associated with symptoms of post-traumatic stress disorders (PTSD)." (PMID 35683610, 2022). "Elevated IL-2, 24 h after injury, is associated more severe early post-concussive symptoms, while elevated plasma IL-10 level at 6 months is associated with more severe posttraumatic stress disorder (PTSD) and mood scores." (PMID 33679762, 2021). "However, the dosage of other more specific factors, such as IL-6 or IL-10, may help to refine the diagnosis of patients at risk of post-traumatic stress disorder." (PMID 31805967, 2019). "Methylation of the AIM2 gene at the site cg10636246 drives the relationship between trauma exposure, posttraumatic stress disorder (PTSD), the level of C-reactive protein (CRP) and other inflammatory mediators, such as IL-6, IL-10, and TNF-α, in the body." (PMID 36742336, 2023). "However, a relationship between PC symptoms and exosomal tau concentration increases was not reported, yet exosomal IL-10 concentrations correlated with post-traumatic stress disorder (PTSD) symptoms." (PMID 38248736, 2023).
Rectal prolapse (8 papers, 2008 to 2025). Protrusion of the rectal mucous membrane through the anus. "As expected, Il10 deficiency was associated with the development of rectal prolapse." (PMID 30410494, 2018). "Nonetheless, compared with the Il10–/–Nfat5+/+ mice, the Il10–/–Nfat5+/– mice had higher DAI scores, more frequent rectal prolapse, and more severe shortening and microscopic pathology of the colon." (PMID 40663408, 2025). "The experiments ended before any difference in body weight was observed (data not shown) because severe rectal prolapse was observed in some Il10 and Nfat5 double-KO (Il10–/–Nfat5+/–) mice." (PMID 40663408, 2025). "Indeed, 2 out of 8 Il10−/−Tcf4Fl/Fl mice and 3 out 8 Il10−/−Tcf4CKO mice showed rectal prolapse, while none of the 7 WT control mice did." (PMID 30410494, 2018).
synovitis (8 papers, 2006 to 2025). Inflammation of a synovial membrane. "Our previous in vivo study of BMNC used to treat experimental synovitis showed that increases in the number of IL-10-producing cells occurred within the first 96 h following BMNC injection." (PMID 37876630, 2023). "Two studies evaluated the effects of IL-10 on histological synovitis." (PMID 35549461, 2022). "Thus, IL-10 acts to prevent long-term subclinical disease and the promotion of self-limiting synovitis." (PMID 25175678, 2014). "PGE2, IL-10, and TNF-α concentrations increased after one hour of LPS-induced synovitis in the present study, however, PGE2 had a higher peak concentration after 8 h." (PMID 32365982, 2020). "IL-10 levels increased significantly after LPS-induced synovitis; however, it was not possible to conclude that the treatments increased the expression of this cytokine." (PMID 32365982, 2020). "Horses with experimental synovitis had no adverse reactions to intra-articular BMNC and treated joints showed marked gross improvement associated with increasing regulatory macrophages and synovial fluid IL-10 concentrations compared with saline-treated controls." (PMID 37876630, 2023).
anxiety disorder (7 papers, 2014 to 2025). A category of psychiatric disorders which are characterized by anxious feelings or fear often accompanied by physical symptoms associated with anxiety. "Despite this, at this time we can conclude that IL-10 might be used as a risk indicator for assessment of susceptibility to anxiety disorder, resulting in early detection of the disease and prompting the initiation of intervention strategies." (PMID 38902708, 2024). "Though several preclinical studies suggest a potential link between IL-10 levels and anxiety disorder, there is a scarcity of clinical studies aimed at evaluating such an association between IL-10 and GAD development." (PMID 38902708, 2024). "Reports have shown that cytokines such as interleukin (IL)-6, tumor necrosis factor-alpha (TNF-α), IL-10, and monocyte chemoattractant protein-1/CCL2 might be well associated with depressive, bipolar, or anxiety disorders." (PMID 29740354, 2018). "Finally, INF-γ:IL-10 ratio displayed significant decrease in high perceived stress(t = −4.606; p = 0.000), state anxiety(t = −5.126; p = 0.000) and trait anxiety(t = −4.670; p = 0.000) groups relative to low counterparts." (PMID 25144199, 2014). "This suggests that CORT, inflammatory factors (IL-6, IL-1β, CD86, TNF-α, TGF-β, IL-10), 5-HT, and GABA may serve as biomarkers for anxiety disorders." (PMID 40078708, 2025). "In individuals with current depressive or anxiety disorders compared to healthy controls, elevated levels were observed in CRP, IL-6, IL-8, IL-18, MCP-1, MIP-1α, MIP-1β, MMP2, and TNF-β, while TNF-α, IL-10, IFN-γ, IL-2, and IL-4 levels either showed no significant elevation or were lower." (PMID 39273641, 2024).
autism spectrum disorder (7 papers, 2017 to 2023). A spectrum of developmental disorders that includes autism, and Asperger syndrome. "Some patients with autism spectrum disorders (ASDs) have an augmented level of proinflammatory cytokines IL-12, IL-6 and IL-1β, while IFNγ and the anti-inflammatory cytokine IL-10 seem to be reduced." (PMID 36835652, 2023). "Our previous research has shown that purified peripheral blood monocytes (PRMo) from individuals who are diagnosed with autism spectrum disorders (ASDs) and have innate immune abnormalities reveal altered interleukin-1ß (IL-1ß)/IL-10 ratios." (PMID 31551826, 2019). "Changes in monocyte cytokine production with toll like receptor (TLR) agonists in subjects with autism spectrum disorders (ASD) were best reflected by the IL-1β/IL-10 ratios in our previous research." (PMID 31554204, 2019). "Previously, we have reported fluctuating interlukine-1ß (IL-1ß)/IL-10 ratios produced by peripheral blood monocytes (PBMo) in some patients with autism spectrum disorders (ASD)." (PMID 29178897, 2017). "Also, it has been demonstrated that vinpocetine suppressed elevated brain levels of IL-6 and TNF-α, and augmented brain level of IL-10, in a rat model of autism spectrum disorder." (PMID 36594060, 2023).
bone cancer (7 papers, 2015 to 2024). A primary or metastatic malignant neoplasm affecting the bone or articular cartilage. "It was also recently revealed that activation of α7 nAChRs produced antinociception in rat models of neuropathic pain and bone cancer pain via spinal microglial expression of IL-10 and β-endorphin." (PMID 33584292, 2020). "We then observed the stimulatory effects of cinobufagin on the expression of IL-10 and subsequent β-endorphin in the spinal cords of bone cancer rats and cultured spinal primary microglial cells." (PMID 32113469, 2020). "Our results illustrate that cinobufagin produces mechanical antiallodynia in bone cancer pain through spinal microglial expression of IL-10 and subsequent β-endorphin following activation of α7-nAChRs." (PMID 32113469, 2020). "It was recently discovered that IL-10 and IL-24, a member of the IL-10 family, were effective in relieving neuropathic pain and bone cancer pain in rats by the promotion of β-endorphin synthesis." (PMID 30981281, 2019). "GLP‐1, GPR40, and α7‐ACh receptor agonists have effectively attenuated pain hypersensitivity in neuropathic pain, inflammatory pain, bone cancer pain, and diabetic pain through spinal microglial autocrine expression of IL‐10 and subsequent expression of β‐endorphin." (PMID 34111331, 2021). "Our behavioral study indicated that stimulating exogenous and endogenous IL‐10 expression have displayed marked pain anti‐hypersensitive activity in animal models of neuropathic pain, peripheral diabetic pain, bone cancer pain, and complete Freund's adjuvant (CFA)‐induced inflammatory pain." (PMID 34111331, 2021). "Particularly, our previous studies also revealed that the spinal microglial IL-10/β-endorphin pathway in bone cancer pain and neuropathic pain mediated the α7 nAChR agonists PHA-543613-, cinobufagin- and lemairamin-induced antinociception, although their chemical structures were different." (PMID 33584292, 2020). "In addition, two groups of female bone cancer pain rats received intrathecal injection of 10 μL of normal saline or 2 μg of the IL-10 antibody followed by 30 μg of cinobufagin 30 min later." (PMID 32113469, 2020). "Lastly, cinobufagin- and the specific α-7 nicotinic acetylcholine receptor (α7-nAChR) agonist PHA-543613-induced microglial gene expression of IL-10/β-endorphin and mechanical antiallodynia in bone cancer pain were blocked by the pretreatment with the specific α7-nAChR antagonist methyllycaconitine." (PMID 32113469, 2020). "Intrathecal cinobufagin also stimulated the gene and protein expression of IL-10 and β-endorphin (but not dynorphin A) in the spinal cords of bone cancer pain rats." (PMID 32113469, 2020). "Our results indicate that XAT decoction can effectively alleviate bone cancer pain, suppress morphine-induced adverse actions, reduce the proinflammatory cytokines IL-1β and TNF-α, and increase the endogenous anti-inflammatory cytokine IL-10." (PMID 26617438, 2015).
brain inflammation (7 papers, 2018 to 2025). "In addition, it has been demonstrated that IL-10 expression in the CNS increases during recovery from brain inflammation, suggesting that IL-10 in CNS is required for inflammatory state remission." (PMID 29500410, 2018). "Glial cell and EC responses during infection indicate that soluble molecules, cytokines, and chemokines such as RANTES, TNF-α, IL-6, IL-10, and MCP-1 among others, favor leukocyte infiltration, worsening brain inflammation." (PMID 31293558, 2019). "In addition, the mRNA expression levels of inflammatory cytokines (Il-6, Il-8, Il-10, Il-18, Il-1β, and Tnf-α) in GPS-infected mice were significantly increased compared to the control group (p < 0.05), which indicated that GPS successfully induced brain inflammation in mice." (PMID 38927100, 2024).
central obesity (7 papers, 2013 to 2025). "In the present study, an increase was observed not only in the pro-inflammatory cytokines, but there was also a reduction in anti-inflammatory cytokines such as klotho and IL-10 in the women presenting central obesity." (PMID 39727499, 2024). "Higher levels of IL-10 in overweight and obese subjects was correlated with BMI and the grade of abdominal obesity." (PMID 36387880, 2022). "General obesity was associated with significantly elevated levels of IL-5, IL-10, IL-12, IL-13, IFN-γ and TNF-α, central obesity with significantly elevated IL-5, IL-10, IL-12, IL-13 and IFN-γ-levels." (PMID 25781614, 2015). "Looking specifically at central obesity, we found higher levels of IL-5, IL-10, IL-12 and IL-13 and IFN-γ in participants with compared to those without central obesity." (PMID 25781614, 2015). "After Bonferroni-correction, IL-5, IL-12 and IL-13 were found to be elevated in both general and central obesity, and IL-10 elevated in the central obese." (PMID 25781614, 2015). "Moreover, after the intervention, subjects in the marine omega-3 group had a higher reduction in the prevalence of abdominal obesity compared to the active placebo group, and better differences between IL-6, IL-10, MCP-1, and RvD1 changes at the end of the study." (PMID 39857130, 2025). "Among the tested cytokines, IL-5, IL-10, IL-12, IL-13 and IFN-γ were elevated in both general and central obesity." (PMID 25781614, 2015). "In the post-hoc ANOVA, subjects with central obesity showed significantly elevated serum concentrations of IL-5, IL-10, IL-12, IL-13 and IFN-γ compared to the group without central obesity (after Bonferroni correction, differences remained significant for all but IFN-γ)." (PMID 25781614, 2015).
cervical intraepithelial neoplasia (7 papers, 2012 to 2025). "Few studies investigated the relationship between CD4,CD8,IL-10, and high-risk human papillomavirus (HPV) with risk of cervical intraepithelial neoplasia (CIN)." (PMID 41142594, 2025). "This study therefore estimated and compared the levels of circulatory IL-4, IL-6, IL-10, TNF-α, and IFN-γ cytokines among adult women identified to have different grades of cervical intraepithelial neoplasia (CIN) and with cervicovaginal infection." (PMID 37635942, 2023).
cholestasis (7 papers, 2017 to 2024). Impairment of the bile flow caused by obstruction within the liver, or outside the liver in the bile duct system. "Levels of IL-6, TNF-α, IL-10, and IL-1β in liver tissue reflect the degree of hepatic inflammation caused by cholestasis, while serum levels of TC, TG, LDL-C, and HDL-C reflect lipid metabolism and oil red O staining visualizes lipid accumulation in liver tissue." (PMID 38523644, 2024). "Among them, TNF-α, IL-6, and IL-10 play important roles in inflammatory responses of the lungs after cholestasis." (PMID 39744639, 2024). "IL-1β, IL-6, TNF-α, and IL-10 are common indices used to assess the inflammatory response, oxidative stress, and apoptosis, among others, in cholestasis." (PMID 36409145, 2022). "In the second phase neutrophils recruited by BDL respond to the respective pathogens by IL-10 production and thereby further augment the anti-inflammatory environment established by cholestasis." (PMID 29953538, 2018). "A recent study has reported that cholestasis can induce anti-inflammatory signals in mice via increased IL-10 production following BDL39." (PMID 30111770, 2018). "Abnormal expression of IL-6, IL-10, IL-17A, IL-17F, TGF-β1 and α-SMA are closely associated with the cholestasis." (PMID 28646179, 2017). "Interestingly, CT_H was less effective than CF_L in reducing IL-6 and increasing IL-10 concentrations, suggesting an antagonism between the anti-inflammatory effects of the two drugs in the treatment of cholestasis." (PMID 38523644, 2024). "It was demonstrated that ANIT-induced cholestasis increased the levels of IL-1β, IL-6, and TNF-α and decreased the levels of IL-10." (PMID 36409145, 2022). "Altogether, these data suggest that cholestasis diminished the MCMV-mediated induction of specific pro-inflammatory chemokines/cytokines and enhanced the expression of the anti-inflammatory interleukin IL-10 in the liver." (PMID 29953538, 2018).